SOD1 (superoxide dismutase 1)
Diseases named in the same sentence as SOD1 in open-access papers (continued):
Sharing a sentence is not in itself a finding about the gene and the disease.
viral infection (43 papers, 2011 to 2025). "Our study shows that the expression of SOD1 is downregulated by IFN-I signaling during viral infection and that loss of SOD1 results in oxidative damage in the liver." (PMID 26588782, 2015). "Researches show evidence of intoxication by heavy metals, environmental and occupational causes, genetic mutations, for example, of superoxide dismutase 1 or of d-amino acid oxidase with accumulation of d-serine in the spinal cord, and viral infections." (PMID 22943439, 2012). "Our results demonstrate that viral infection causes an early decrease in SOD1 and there is significant oxidative stress in infected cells." (PMID 21655261, 2011). "The downregulation of SOD1 transcription may be due to the decreased promoter activity caused by virus infection." (PMID 26761025, 2016). "Transient expression of NbCu/Zn-SOD-1 gene increased SOD activity in N. benthamiana, thereby improving the defense of N. benthamiana against virus infection." (PMID 40756210, 2025). "Together, these results suggest that SOD1 plays a general protective role in the liver during viral infection." (PMID 26588782, 2015). "Together, these results reveal an early tissue-protective effect for the blockade of IFNAR1 and highlight the role of IFN-I in driving oxidative liver damage induced by viral infections both in Sod1−/− and in WT mice." (PMID 26588782, 2015). "To study the effects of the virus infection dose on the observed pathology, we infected Sod1−/− and WT mice with either a low dose of LCMV strain clone 13 or with another LCMV strain ARM that is usually cleared within 8 days." (PMID 26588782, 2015). "This prompted us to further investigate the potential role of IFN-I signaling in SOD1-dependent liver damage upon viral infection." (PMID 26588782, 2015). "The viral infection leads to the downregulation of specificity protein 1 (Sp1), a dominant cis-acting regulatory element of SOD1, which reduces the quantity and activity of SOD1." (PMID 38106478, 2023). "In addition, we found that virus infection broadly affected the expression of the antioxidant enzymes such as SOD1, CAT, GPX4, and SOD2 at both mRNA and protein levels." (PMID 31011285, 2019). "This is in consistent with a previous study defining SP1 could be influenced by virus infection, which is a principal factor for SOD1 transcription." (PMID 26761025, 2016). "Moreover, treatment with rIFN-α downregulated Sod1 expression in WT mice, similar to what we observed upon viral infection, suggesting a direct involvement of IFN-I signaling in the regulation of Sod1 expression." (PMID 26588782, 2015). "To investigate whether the SOD1-mediated protection of the liver constituted a general host mechanism during viral infections, we infected Sod1−/− and WT mice with the cytolytic murine coronavirus MHV." (PMID 26588782, 2015). "This functional circuit of IFN-I, SOD1, and oxidative stress provides mechanistic insights into the inflammatory and tissue-damaging processes in the liver upon viral infection, as well as a deeper understanding of the role of oxidative stress in viral hepatitis." (PMID 26588782, 2015). "We next evaluated the effect of lowered SOD1 level during a viral infection on apoptosis." (PMID 21655261, 2011). "Next, to confirm whether IFNβ overproduction during viral infection is a common phenomenon in all ALS patients, we examined IFNβ production by cells from several ALS patients with mutations in the ALS-causative genes, SOD1, FUS, ANG, FIG4, and TARDBP." (PMID 37352136, 2023). "Thus, SOD1 is required to prevent oxidative damage in the liver upon viral infection." (PMID 26588782, 2015). "Currently identified potential mechanisms of ALS consist of aberrant RNA processing, superoxide dismutase 1 (SOD1) toxicity, cytoskeletal disorders, mitochondrial dysfunction, viral infections, among others." (PMID 39643909, 2024).
viral infection (continued). "The expression of antioxidant enzymes including superoxide dismutase 1 (SOD1), SOD2, catalase (CAT), and glutathione peroxidase 4 (GPX4) was differentially affected following the virus infection." (PMID 31011285, 2019). "Moreover, some genes related to protein secretion and reactive oxygen species pathways like MAPK1, RAB14, RAB22A, SOD1, and CAT were dysregulated in COVID-19 versus other-viral diseases." (PMID 35922752, 2022). "SOD1, SOD3, catalase, and Nrf2 were downregulated by viral infection." (PMID 26761025, 2016). "Sod1−/− mice exhibited increased inflammation and aggravated liver damage upon viral infection, which was independent of T and NK cells and could be ameliorated by antioxidant treatment." (PMID 26588782, 2015). "Strikingly, we were able to observe strong cytopathic effect in the SOD1-depleted cells as early as 24 h post infection (data not shown) suggesting that a combination of lowered SOD1 levels and a viral infection could push cells faster into apoptosis." (PMID 21655261, 2011).
Hepatic steatosis (42 papers, 2014 to 2026). Steatosis is a term used to denote lipid accumulation within hepatocytes. "Mice that are deficient in superoxide dismutase 1 (Sod1), an antioxidative enzyme, are susceptible to developing liver steatosis." (PMID 30050648, 2018). "The PPIs could help explain partially a puzzling observation that knockouts of Sod1 and Gpx1, two genes encoding redox enzymes with similar functions in scavenging free radicals, led to different severities in many phenotypes, including hepatic steatosis." (PMID 36834640, 2023). "Compared with HFHC, both CAB and HECAB reduced serum insulin and HOMA-IR, attenuated hepatic steatosis, increased SOD1 and CAT, and reduced NF-κB, IL-6, TNF-α, and IL-1β, whereas GPx1 remained unchanged." (PMID 42193214, 2026). "Prdx4 and superoxide dismutase 1 (Sod1) double-knockout mice (Prdx4−/y;Sod−/−) show more severe liver phenotypes, such as aggravated liver steatosis and liver failure, at a relatively young age compared with those of wild-type, Prdx4−/y, and Sod−/−." (PMID 32098329, 2020). "In addition, long-term feeding of ethanol diet for 42 days to C57BL/6 mice promoted hepatic steatosis, inflammation, and apoptosis with a concomitant upregulation of hepatic SOD1 and GPX." (PMID 41154722, 2025). "The findings reported here indicate that, although the deletion of the Prdx4 gene alone had little effect on liver physiology, the deletion of Sod1 together with Prdx4 resulted in an enhanced level of aggravated liver damage compared to Sod1−/− mice, which reportedly develop liver steatosis." (PMID 30050648, 2018). "However, the role of SOD1 in alcohol-induced hepatic steatosis remains controversial." (PMID 41154722, 2025). "Thus, it is likely that both prolonged oxidative stress and ER stress are synergistically involved in stimulated lipogenesis but the inability to secrete lipoproteins from the liver, thereby resulting in the development of liver steatosis much more severe in the DKO mice than in the Sod1−/− mice." (PMID 30050648, 2018). "To investigate the protective effects of ABE on inflammation and oxidative stress in hepatic steatosis, we examined hepatic LCN2, HO-1, and SOD1 expressions." (PMID 36501079, 2022). "Curcumin treatment alleviates the severity of hepatic steatosis by blocking the NF-κB signaling pathway through the inhibition of O-GlcNAcylation and enhancing antioxidant systems, including SOD1 (superoxide dismutase 1), GPx (glutathione peroxidase), and CAT (catalase)." (PMID 37375652, 2023). "Moreover, selenium deficiency could decrease the expression of intracellular antioxidant enzymes, including Superoxide dismutase-1 (SOD1), which results in the development of fatty liver." (PMID 35624786, 2022).
colorectal cancer (41 papers, 2011 to 2025). A primary or metastatic malignant neoplasm that affects the colon or rectum. "For example, the selective killing of RAD54B-deficient colorectal cancer cells by PARP1 inhibitors is enhanced by silencing SOD1." (PMID 40001471, 2025). "Similar synthetic lethal relationships were found in BLM- and CHEK2-deficient colorectal cancer cells, which were selectively killed by SOD1 silencing." (PMID 40001471, 2025). "•Age and TNM staging had significant association with SOD1 level among the colorectal cancer (CRC) patients." (PMID 32994983, 2020). "PARP1 inhibition along with superoxide dismutase 1 (SOD1) inhibition could promote the synthetic lethal killing of RAD54B-deficient colorectal cancer cells." (PMID 32711558, 2020). "Consequently, it can be assumed that the tested compounds have a higher affinity for SOD2 than SOD1, and thus, with prolonged exposition, a lower amount of the protein can be expected, which translates into reduced antioxidant capacity of colorectal cancer cells and associated cell death." (PMID 39195258, 2024). "Based on these findings, SOD1 inhibition was proposed as a novel therapeutic approach for colorectal cancers with RAD54B defects." (PMID 40001471, 2025). "The expression of the antioxidant enzymesuperoxide dismutase (SOD-1) was evaluated to investigate the oxidativestress response in colorectal cancer cells." (PMID 41427204, 2025). "In present study we investigate the possible association between polymorphisms of superoxide dismutase 1 (SOD1, OMIM: 147450) and catalase (CAT, OMIM: 115500) genes and the risk of colorectal cancer (CRC)." (PMID 28775994, 2017). "Additional studies have shown that increases in reactive oxygen species following SOD1 (Superoxide Dismutase 1) silencing and inhibition induces SL killing in colorectal cancer cells harboring defects in established CIN genes, like RAD54B, BLM, and CHEK2." (PMID 29104272, 2017). "The accumulation of ROS in colorectal cancer cells might be explained by decreased expression of SOD1, which is assumed to exert protective effects on cells damaged by ROS." (PMID 30763370, 2019). "Thus, it can be considered that SOD1, SOD2, or SOD3 play an important role in colorectal cancer, lung adenocarcinoma, and other cancers." (PMID 37759978, 2023). "Finally, future studies should incorporate the distinct roles of different SOD isoforms (SOD1, SOD2, and SOD3) in colorectal cancer prognosis, as their specific contributions may influence biomarker development and clinical applications." (PMID 41479776, 2025). "Of note, we do not imply that inhibition of SOD1 might represent an exclusive mechanism of salinomycin to treat colorectal cancer cells." (PMID 30763370, 2019).
COVID-19 (41 papers, 2020 to 2026). A disease caused by infection with severe acute respiratory syndrome coronavirus 2. "In the present study, a significant increase in CAT and SOD1 expression and activity was observed in vaccinated COVID-19-positive placentae compared to both unvaccinated and control COVID-19-negative patients." (PMID 39768279, 2024). "Alteration of redox homeostasis through the alteration of sodium dismutase (SOD1), an enzyme that catalyzes the conversion of superoxide to hydrogen peroxide and oxygen, is reported in COVID-19 patients." (PMID 38365632, 2024). "For the first time, we also demonstrated that SARS-CoV-2 vaccination significantly increased the antioxidant enzymes CAT and SOD1 in the placentae of COVID-19-positive patients, eliciting a boost in placental protection against OxS." (PMID 39768279, 2024). "Vaccination significantly increased placental CAT and SOD1 expression and activity in COVID-19-positive women, suggesting enhanced antioxidant defense." (PMID 39768279, 2024). "We found that the amounts of Cp, Tf, HPX, LCN2, and SOD1 increased in PBMCs isolated from COVID-19 patients, compared to both the long-COVID group and the control group." (PMID 36613462, 2022). "CAT overexpression was accompanied by a significant increase in SOD1 mRNA levels in v-COVID-19 (p < 0.001, 3.2-fold increase; p = 0.001, 2.7-fold increase) and u-COVID-19 (p < 0.001, 2.1-fold increase; p = 0.017, 1.8-fold increase) placentae compared to the v-CTRL and u-CTRL subgroups." (PMID 39768279, 2024). "Moreover, SOD1 gene expression levels were significantly over-expressed in the v-COVID-19 placentae relative to the u-COVID-19 placentae (p = 0.04, 1.5-fold increase)." (PMID 39768279, 2024). "Concerning the comparison between COVID-19 and long-COVID patients, generally decreased levels of all iron-related metabolism proteins were reported in long-COVID patients, but only Cp, Tf, and SOD1 were found to be significantly altered." (PMID 36613462, 2022). "In line with this theory, in our cohort of long-COVID patients, we found a decreasing trend of antioxidant proteins, such as Cp, Tf, and SOD1, in comparison to COVID-19 patients and healthy controls, and a significant increase in HPX levels compared to the healthy controls." (PMID 36613462, 2022). "Serum from patients with severe COVID-19 significantly upregulated genes involved in the cellular antioxidant response in HUVEC, including NFE2L2, HMOX1, SOD1, CAT, GPX1, and GSR." (PMID 41583455, 2025). "Specifically, individuals with the SOD1 G, SOD2 T, and CAT C combination had higher odds of severe COVID-19 (p = 0.0045; OR = 2.84), suggesting a collective, rather than isolated, influence of these antioxidant genes." (PMID 41209585, 2025). "SOD1 gene overexpression was accompanied by a significant increase in SOD enzymatic activity in the v-COVID-19 (p = 0.007, 1.3-fold increase) and u-COVID-19 (p = 0.002, 1.2-fold increase) subgroups compared to the v-CTRL subgroup." (PMID 39768279, 2024). "The expression levels of Nrf2, CAT, SOD1, and SOD2 were increased in COVID-19 patients compared to healthy subjects." (PMID 36493512, 2023). "Remarkably, the results indicated decreased expression of Nrf2, CAT, SOD1, and SOD2 (P-value <0.02) as well as GP91PHOX (P-value <0.02) in COVID-19 patients compared to controls." (PMID 36493512, 2023). "Regarding redox enzymes, we found no regulation of GR but a downregulation of SOD-1 in samples of COVID-19 patients compared to control groups, suggesting the possible degradation of this enzyme in RBCs from COVID-19 patients, which is in line with other reports." (PMID 35181867, 2022). "Regarding redox enzymes, superoxide dismutase-1 (SOD-1), but not glutathione reductase protein expression was significantly decreased in samples from COVID-19 patients compared to healthy donors and convalescent patients." (PMID 35181867, 2022).
COVID-19 (continued). "SOD1 and GSR showed decreased levels of gene expression in the placentas of both COVID-19 groups compared to controls, though not significantly." (PMID 34679654, 2021).
ischemic stroke (40 papers, 2013 to 2026). A stroke disorder caused by obstruction of blood flow to the brain, due to thrombotic (local blood clot formation) or embolic (due to a blood clot or other material traveling from another site) event. "The SNP rs7655372 in the SOD3 gene was associated with an increased risk of ischemic stroke, and the SNP rs17880487 in the SOD1 gene was associated with an increased risk of cardiovascular mortality." (PMID 36875474, 2023). "In a previous study, six single-nucleotide polymorphisms (SNPs) within SOD genes were investigated to determine their association with ischemic stroke: rs17880487 and rs80265967 in SOD1, rs4880 and rs2842960 in SOD2, and rs2695232 and rs7655372 in SOD3." (PMID 36875474, 2023). "In diabetes patients who are susceptible to thrombotic events, such as ischemic stroke, lower GSH, GPx, and SOD-1 levels are noted within platelets, while administration of N-acetylcysteine can reduce the risk of ischemic stroke via enhancing the platelet antioxidant enzyme activity." (PMID 36439687, 2022). "Several studies with animal models of ischemic stroke (focal or global cerebral ischemia) have demonstrated the neuroprotective potential of SOD1." (PMID 24448401, 2014). "Recently, SOD1 has been selected to genetically modify neural stem cells as its overexpression has improved their survival following intracerebral administration in rodent models of ischemic stroke." (PMID 24448401, 2014).
myocardial ischemia (40 papers, 2011 to 2026). A disorder of cardiac function caused by insufficient blood flow to the muscle tissue of the heart. "Another study found that Irisin attenuated oxidative stress injury by activating superoxide dismutase 1 (SOD1) in cardiomyocytes and repaired mitochondrial function destroyed by myocardial ischemia reperfusion." (PMID 36111165, 2022). "The greater protective effects of combined use of PEP-1-SOD1 and PEP-1-CAT against myocardial ischemia-reperfusion injury are due to the combined function of SOD1 and CAT." (PMID 21600015, 2011). "The activation of PPARα protects myocardial cells by increased expression and activation of superoxide dismutase (SOD1, SOD2) and catalase and suppresses the generation of ROS in myocardial ischemia." (PMID 30911353, 2019).